FSTL3 (follistatin like 3)
Description:
Isoform 1 or the secreted form is a binding and antagonizing protein for members of the TGF-beta family, such as activin, BMP2 and MSTN. Inhibits activin A-, activin B-, BMP2- and MSDT-induced cellular signaling; more effective on activin A than on activin B. Involved in bone formation; inhibits osteoclast differentiation. Involved in hematopoiesis; involved in differentiation of hemopoietic progenitor cells, increases hematopoietic cell adhesion to fibronectin and seems to contribute to the adhesion of hematopoietic precursor cells to the bone marrow stroma. Isoform 2 or the nuclear form is probably involved in transcriptional regulation via interaction with MLLT10.
Synonyms: FLRG; FSRP
Tractability: Antibody: its Gene Ontology location is reachable by antibodies, with high confidence; UniProt places it where antibodies can reach, with medium confidence; UniProt predicts a signal peptide or a membrane-spanning region.
Gene: Protein-coding gene on chromosome 19 (676,392 to 683,392, forward strand). Ensembl gene ENSG00000070404.
Subcellular location: Secreted (Isoform 1); Nucleus (Isoform 2)
Subcellular location (Human Protein Atlas): Nucleoplasm; Predicted to be secreted
Pathways (Reactome):
Metabolism of proteins: Post-translational protein phosphorylation; Regulation of Insulin-like Growth Factor (IGF) transport and uptake by Insulin-like Growth Factor Binding Proteins (IGFBPs)
Signal Transduction: Antagonism of Activin by Follistatin
Gene Ontology:
Molecular function: activin binding; fibronectin binding; protein binding
Biological process: hematopoietic progenitor cell differentiation; negative regulation of activin receptor signaling pathway; negative regulation of BMP signaling pathway; negative regulation of osteoclast differentiation; negative regulation of transmembrane receptor protein serine/threonine kinase signaling pathway; positive regulation of cell-cell adhesion; positive regulation of transcription by RNA polymerase II; regulation of transcription by RNA polymerase II; cell differentiation; regulation of BMP signaling pathway
Cellular component: extracellular region; nucleoplasm; nucleus; endoplasmic reticulum lumen
Genetic constraint (gnomAD): Loss-of-function variants: 17 observed, 15.8 expected, observed/expected ratio (o/e) 1.08, 90% interval 0.74 to 1.6. The synonymous counts are far from expectation, so gnomAD's model fits this gene poorly and the ratio says little. Missense variants: 322 observed, 266.88 expected, observed/expected ratio (o/e) 1.21, 90% interval 1.1 to 1.32. Synonymous variants: 170 observed, 114.37 expected, observed/expected ratio (o/e) 1.49, 90% interval 1.31 to 1.69.
Homologues: Orthologues: chimpanzee FSTL3 (99% identical), pig FSTL3 (90% identical), dog FSTL3 (89% identical), guinea pig FSTL3 (83% identical), mouse Fstl3 (81% identical), rat Fstl3 (78% identical), macaque FSTL3 (67% identical), tropical clawed frog fstl3 (58% identical), zebrafish fstl3 (52% identical). Paralogues in human: FST (43% identical), SPINK5 (20% identical), FSTL5 (19% identical), FSTL4 (19% identical), FSTL1 (14% identical), SPINK6 (4% identical).
Diseases named in the same sentence as FSTL3 in open-access papers:
FSTL3 is named in the same sentence as 80 diseases in open-access papers, as found by Europe PMC text mining. Sharing a sentence is not in itself a finding about the gene and the disease. The quoted sentences say what the papers report.
breast carcinoma (13 papers, 2009 to 2024). "FSTL3 has been reported to participate in tumorigenesis and associate with nuclear grade and tumor size in breast cancer." (PMID 35511773, 2022). "FSTL-3 has also been reported to be independently associated with malignant progression of breast cancer and tumor size." (PMID 33195193, 2020). "In this context, the diagnostic and prognostic value of serum FSTL3 levels in breast cancer progression should be investigated in future studies." (PMID 28178680, 2017). "FSTL3 also plays a role in the development of different types of malignancies, including hepatocellular carcinoma, breast cancer, and NSCLC." (PMID 38240936, 2024). "This is somewhat counterintuitive given that activin A inhibits and FSTL3 stimulates the in vitro proliferation of human breast cancer cells." (PMID 28178680, 2017). "Overall, even though compelling data suggest that FSTL3 stimulates breast cancer proliferation, the present evidence suggests that the pattern of FSTL3 expression in the tumor epithelium does not determine the aggressiveness of the disease." (PMID 28178680, 2017). "Previous studies have shown reduced proliferation of breast cancer cell lines upon activin treatment or FSTL3 silencing in vitro." (PMID 28583174, 2017). "Here we evaluate FSTL3 as a prognostic tool and its relation with clinical and pathological features of breast cancer." (PMID 28178680, 2017). "We have previously shown FSTL3 overexpression in invasive breast cancers, but its clinical relevance remained unexplored." (PMID 28178680, 2017). "a Follistatin-like 3 (Fstl3) is downregulated in HER 2/Neu-induced mouse mammary tumors compared with normal mammary glands." (PMID 28583174, 2017). "It has also been reported that the serum level of FSTL3 is higher in breast cancer patients." (PMID 36807490, 2023). "However, in a subsequent study, FSTL3 levels in breast cancer were inversely related to tumour size and nuclear grade and did not correlate with disease survival." (PMID 36807490, 2023). "Furthermore, FSTL3 was found abundantly expressed in cell lung cancer and breast cancer and participates in tumor progression, containing invasion and metastasis." (PMID 36251702, 2022). "Invasive breast cancer specimens had higher area and intensity of FSTL3 mRNA and protein staining in tumor epithelial cells compared to other less invasive breast proliferative diseases, suggesting that FSTL3 might be involved in breast cancer progression." (PMID 28178680, 2017). "Therefore, we designed the present study in order to evaluate FSTL3 as a prognostic tool and its relation with clinical and pathological features of breast cancer." (PMID 28178680, 2017). "This study evaluated breast cancer FSTL3 expression in the clinical setting." (PMID 28178680, 2017). "FSTL3 also binds and neutralizes other growth factors involved in cancer progression such as myostatin and bone morphogenetic proteins, highlighting the need of better characterization of FSTL3 actions and prognostic value in breast cancer and other malignancies." (PMID 28178680, 2017). "Moreover, FSTL3 served as a surrogate marker in breast cancer and was the only variable that could distinguish a benign breast mass from a malignant one." (PMID 33228590, 2020). "Thus, our data suggest that FSTL3 expression may be more abundant in the slower proliferating tumors, challenging our previous assumption that this protein would contribute to human breast cancer growth." (PMID 28178680, 2017). "As in human breast cancer, we found that FST was profoundly repressed in mammary tumors collected from transgenic mice expressing the Her2/Neu proto-oncogene in the mammary epithelia (MMTV-Neu), as was Fstl3." (PMID 28583174, 2017). "We conclude that tumor tissue expression of FSTL3 is not a prognostic factor of clinical relevance for breast cancer patients." (PMID 28178680, 2017). "FSTL3 expression also showed no prognostic value in breast cancer patients." (PMID 28178680, 2017).
breast carcinoma (continued). "Thus, a contribution of systemic FSTL3 to breast cancer growth cannot be ruled out." (PMID 28178680, 2017).
preeclampsia (13 papers, 2013 to 2025). Preeclampsia is a hypertensive disorder of pregnancy that is characterized by new-onset hypertension with proteinuria presenting after 20 weeks of gestation, and depending on mild or severe forms may initially present with severe headache, visual disturbances, and hyperreflexia. "In vitro, FSTL3 is transcriptionally induced by hypoxic stress in cultured trophoblasts, consistent with deficient uteroplacental perfusion as an inciting event in preeclampsia pathogenesis." (PMID 38099221, 2023). "Clinical samples revealed that FSTL3 levels were increased in the second trimester, which was related to an increased risk of developing preeclampsia." (PMID 35780124, 2022). "In particular, FSTL3 can promote adhesion and infiltration of trophoblast cells, which is associated with preeclampsia development." (PMID 36325361, 2022). "Data obtained from clinical samples showed that FSTL-3 was elevated in the second trimester, which was associated with an increased risk in developing preeclampsia." (PMID 33195207, 2020). "In this regard, an understanding of the regulatory process of trophoblast invasion and the role of FSTL3 in trophoblast invasion will facilitate the development of diagnostic strategies for preeclampsia." (PMID 33195207, 2020). "Furthermore, FSTL3 expression is elevated in trophoblasts in response to hypoxia (a hallmark of preeclampsia), and FSTL3 deficiency impairs trophoblast invasion." (PMID 35780124, 2022). "Further elucidating the molecular interactions of FSTL3 and integrating these findings through systems biology approaches will provide insights into its utility as a biomarker or therapeutic target in preeclampsia." (PMID 38099221, 2023). "Follistatin serum levels in women with preeclampsia are significantly reduced at the late second and third trimesters (25+0–40+0 weeks of gestation), though changes in maternal serum follistatin-like 3 remain uncertain." (PMID 37595293, 2023). "While the predictive value of first trimester circulating FSTL3 levels remains inconclusive, the collective data support a contributory role for FSTL3 in preeclampsia pathogenesis." (PMID 38099221, 2023). "COL17A1, FLT1, FSTL3, and SERPINA3 were identified as diagnostic genes of preeclampsia and validated in the GSE44711 datasets." (PMID 35528613, 2022). "They observed that human umbilical cord mesenchymal stem cell-released exosomes exerted a protective effect on preeclampsia by mediating the transmission of miR-140-5p, primarily by targeting FSTL3." (PMID 36325361, 2022). "FSTL3 is highly expressed in patients with preeclampsia and positively regulates trophoblast function." (PMID 36325361, 2022). "Our study identified COL17A1, FLT1, FSTL3, and SERPINA3 as novel diagnostic biomarkers for preeclampsia patients." (PMID 35528613, 2022). "In our previous studies, we observed that the serum levels and placental expression of FSTL3 were significantly increased in women with preeclampsia." (PMID 33195207, 2020). "As the antagonist of GDF8, FSTL3 was under-expressed in the first trimester placental tissues of preeclampsia." (PMID 33195207, 2020). "In fact, GDF8 and FSTL3 are both induced and increased in patients with preeclampsia by a defective trophoblast invasion." (PMID 33195207, 2020). "In the in vivo system, the interaction between GDF8 and FSTL3 is more complicated than we expected, especially when we discuss their roles in the development of preeclampsia." (PMID 33195207, 2020). "Specificity to preeclampsia prediction or detection will likely require FSTL-3 levels to be combined with other clinical, demographic, and molecular biomarkers." (PMID 26580600, 2015). "Follistatin-like 3, on the other hand, yielded lower values in the ROC analysis for preeclampsia prediction; AUC of 0.650–0.750 between 9+0–13+6 weeks of gestation, an AUC of 0.522 between 11+0–14+0 weeks of gestation and an AUC of 0.706 between 24+0–28+0 weeks of gestation." (PMID 37595293, 2023).
preeclampsia (continued). "Many studies have shown that MSTN and FSTL3 may have a role in the regulation of normal placentation and preeclampsia." (PMID 35780124, 2022). "Hypoxia is a characteristic feature of preeclampsia; trophoblasts highly express FSTL3 after using hypoxia-mimetic agents, and hypoxia-inducible factor-1 alpha (HIF1α) may be involved in promoting FSTL3 expression." (PMID 36325361, 2022). "The dynamic change in myostatin is more than that in FSTL3 in women with preeclampsia." (PMID 36325361, 2022). "FSTL3 functions in signal transduction of activin A which was elevated in preeclampsia." (PMID 26580600, 2015). "Remaining mRNA from the microarray samples were submitted to quantitative polymerase chain reaction (qPCR) studies, demonstrating LAIR2 and FSTL3 were each lower with large effect size in preeclampsia compared with uncomplicated pregnancy, which was consistent with the microarray results." (PMID 26580600, 2015). "Functional investigations demonstrate that FSTL3 knockdown promotes apoptosis and inhibits proliferation, migration, invasion, and lipid accumulation in trophoblasts—cellular phenotypes that mirror the shallow trophoblast invasion and abnormal placentation observed in preeclampsia." (PMID 38099221, 2023). "The distinct upregulation of COL17A1, SERPINA3, FSTL3, and FLT1 in preeclampsia was further demonstrated." (PMID 35528613, 2022). "Maternal serum levels and placental expression of FSTL3 and MSTN were found to be considerably higher in women with preeclampsia." (PMID 35780124, 2022). "Studies have shown that the maternal serum levels and placental expression of FSTL3 and GDF8 were significantly increased in women with preeclampsia." (PMID 33195207, 2020). "Our findings together with previous findings suggested COL17A1, FLT1, FSTL3, and SERPINA3 may influence the immune function of preeclampsia patients." (PMID 35528613, 2022). "However, during the later stage of gestation, maternal serum levels of both FSTL3 and GDF8 were significantly elevated in women with preeclampsia." (PMID 33195207, 2020). "Furthermore, we have demonstrated that the expression of FSTL3 is upregulated in trophoblasts under the stimulus of hypoxia (one of features of preeclampsia) and that the lack of FSTL3 inhibits trophoblast invasion." (PMID 33195207, 2020). "In this period, FSTL3 was decreased, while GDF8 was increased, indicating that the lack of FSTL3 might be a potential pathogenic factor of preeclampsia as the decreased level of FSTL3 insufficiently induced trophoblast invasion." (PMID 33195207, 2020).
colorectal cancer (10 papers, 2021 to 2025). A primary or metastatic malignant neoplasm that affects the colon or rectum. "Analysis of associations between clinicopathological features and FSTL3 expression in patients with colorectal cancer." (PMID 36807490, 2023). "In colorectal cancer, FSTL3 promotes immune evasion by inhibiting c‐Myc degradation, ultimately contributing to the failure of immunotherapy." (PMID 41395115, 2025). "A recent study in colorectal cancer suggested that FSTL3 may contribute to immune evasion and showed that FSTL3 overexpression in malignant cells was linked to poor clinical survival outcomes with anti-PD1 therapy." (PMID 41029436, 2025). "In addition to its role in colorectal cancer, FSTL3 is also overexpressed in human gastric cancer cells and promotes their invasion of other tissues." (PMID 36325361, 2022). "However, the clinico-pathological significance, biological role and molecular mechanism of FSTL3 in colorectal cancer (CRC) is still unclear." (PMID 34395416, 2021). "YAP1 can transactivate FSTL3, thereby forming a positive feedback loop that promotes EMT, aerobic glycolysis, and the invasion and metastasis of colorectal cancer cells." (PMID 36325361, 2022). "This correlation between overexpression of FSTL3 and poor outcome may not be unique to ascites nor ovarian cancer as it was also observed at the transcriptional level across multiple solid tumor types including pancreatic, lung, and colorectal cancers through analysis of data from the TCGA." (PMID 41029436, 2025).
Obesity (10 papers, 2014 to 2024). Accumulation of substantial excess body fat. "Recently, FSTL3 has been shown to regulate numerous BP such as cellular differentiation, aging, obesity development, atherosclerosis progression, and tumor progression." (PMID 38240936, 2024). "Besides, hypertension and diabetes are linked by CXCL8, HLA-B, and KANSL1; diabetes and obesity are linked by TRIM26 and MMP8; hypertension and obesity are linked by PLA2G7, FSTL3, STC2, and BCL2A1." (PMID 36685671, 2023). "Obesity negatively impacted the sWAT-MSC secretome, since its anti-oxidant (GCL, Prdx5, Prdx6) and tissue development (Ang, Angptl4, Fstl3, Pgf) activities were lost, while factors promoting osteoporosis and negative vessel remodeling were acquired." (PMID 32727501, 2020). "Obesity negatively impacted sWAT-MSC secretome: the anti-oxidant (GCL, Prdx5, Prdx6) and tissue development (Ang, Angptl4, Fstl3, Pgf) activities were lost, while factors promoting osteoporosis and negative vessel remodeling were acquired." (PMID 32727501, 2020). "Additionally, genes FSTL3, QSOX1 and SERPINE2 could serve as novel obesity-related biomarkers, as they have been shown to be uniquely enriched in the placenta, and we detected them as down-regulated among the placentas from obese women." (PMID 28125591, 2017).
diabetes (7 papers, 2014 to 2025). "The results indicated that in cases with high expression of FABP4, CDR2L, and FSTL3, immune-related pathways associated with diabetes and colon cancer were significantly enriched." (PMID 40595026, 2025). "The study aimed to investigate an association of increased liver fibrosis with acute myocardial infarction (AMI), and to investigate the mediating effect of serum follistatin-like protein 3 (FSTL3) on the association in patients with type 2 diabetes mellitus (T2DM)." (PMID 37904173, 2023). "By integrating multi-omics data from public repositories and applying machine learning-driven feature selection, we identified three core biomarkers—FABP4,CDR2L,and FSTL3 that independently predicted overall survival in CRC patients with diabetes." (PMID 40595026, 2025). "Our findings establish FABP4, CDR2L, and FSTL3 as pivotal regulators at the CRC-diabetes interface, with dual utility as prognostic indicators and predictors of immunotherapy efficacy." (PMID 40595026, 2025). "We observed evidence of colocalization for observed MR associations for SPON1, CCL15, and FSTL3 with multiple outcomes; for SVEP1 with HF; and for NRP1 with diabetes and CHD." (PMID 38225249, 2024). "Neutralizing antibodies to FSTL3 also show potential clinical application in the treatment of diabetes and muscle wasting." (PMID 36325361, 2022). "Inhibitors and neutralizing antibodies against FSTL3 have been used in the treatment of diabetes and muscle wasting in vivo." (PMID 36325361, 2022). "We observed MR evidence for associations between genetically regulated levels of 7 proteins and HF risk factors including: SPON1, CCL15, and ITIH3 with hypertension; SVEP1 and SPON1 with atrial fibrillation; FSTL3 and NRP1 with diabetes; and APOF, CCL15, ITIH3, and NRP1 with CHD." (PMID 38225249, 2024).
heart failure (7 papers, 2020 to 2022). Inability of the heart to pump blood at an adequate rate to meet tissue metabolic requirements. "The expression levels of FSTL3 positively correlated with α-skeletal actin and brain natriuretic peptide, both markers of heart failure severity." (PMID 36325361, 2022). "The data showed that the elevated expression of FSTL1 and FSTL3 was a marker of heart failure and was detected within 30 min by synthetic Au NPs, which was accurate and rapid." (PMID 36557991, 2022). "Elevated levels of FSTL3 have been detected in the myocardium of patients with heart failure." (PMID 36325361, 2022). "Another important gene that is observed to be upregulated in patients with heart failure is FSTL3." (PMID 32878883, 2020). "Alternatively, FSTL3 expression levels could be used as a biomarker for heart failure." (PMID 36325361, 2022).